YAP1 (Yes1 associated transcriptional regulator)
Diseases named in the same sentence as YAP1 in open-access papers (continued):
Sharing a sentence is not in itself a finding about the gene and the disease.
pancreatic cancer (continued). "In addition, YAP1 promotes the expression of IL‐6 through regulating immune reprogramming in pancreatic cancer." (PMID 37287755, 2023). "The median survival time of patients with high YAP1 expression is shorter than that of patients with colorectal and pancreatic Cancer, and the difference is statistically significant, and the difference is not statistically significant in patients with other types of tumor." (PMID 35911146, 2022). "YAP1 expression levels are associated with poor patient outcome and the squamous subtype in PDAC, with YAP acting to bypass KRAS dependency in pancreatic cancer cell lines, suggesting an ability to induce transcription of targets up-regulated on aberrant KRAS signalling." (PMID 35119068, 2022). "YAP1 may be a molecular marker that effectively predicts the survival of malignant digestive tumors, especially pancreatic cancer, and is a potential therapeutic target for malignant digestive tumors." (PMID 35911146, 2022). "WDR3 silencing could inactivate the Hippo signaling pathway by decreasing YAP1 expression in pancreatic cancer cells." (PMID 33648545, 2021). "A previous study showed that YAP1 deletion downregulated SAM in primary pancreatic tumour cells." (PMID 33803512, 2021). "Therefore, YAP1 expression correlated with migration and invasion in three independent pancreatic cancer cell lines." (PMID 34094936, 2021). "Furthermore, WDR3 induced YAP1 expression by interacting with GATA4 and inducing the nuclear translocation of GATA4, the transcription factor of YAP1, in pancreatic cancer cells." (PMID 33648545, 2021). "In conclusion, we proved that GATA4, acting as a transcription factor, could transcriptionally upregulate YAP1 expression in pancreatic cancer cells." (PMID 33648545, 2021). "Interestingly, our study also confirmed that YAP1 is overexpressed in pancreatic cancer and the prognosis of PC patients with a high YAP1 expression is poor." (PMID 34353343, 2021). "Therefore, the mechanisms by which YAP1 functions in the immune microenvironment in pancreatic cancer deserve further study." (PMID 34150844, 2021). "Accordingly, these previous observations, together with our study, suggested that the YAP1 could be a promising therapeutic strategy to treat pancreatic cancer." (PMID 34257617, 2021). "We demonstrated that WDR3 could regulate YAP1 expression in pancreatic cancer cells, but the clinical relationship between WDR3 and YAP1 in human pancreatic cancer specimens remains unclear." (PMID 33648545, 2021). "Interestingly, our results identified a protein interaction between WDR3 and GATA4 that led to the regulation of GATA4 nuclear translocation and YAP1 expression in pancreatic cancer." (PMID 33648545, 2021). "Therefore, exploring methods to inhibit YAP1 expression is essential for improving pancreatic cancer therapy." (PMID 33648545, 2021). "YAP1 has been shown to overcome KRAS blockade to prompt pancreatic cancer growth in murine models." (PMID 33777798, 2021). "Therefore, all these results suggested a positive correlation between the expression levels of WDR3 and YAP1 in pancreatic cancer specimens." (PMID 33648545, 2021). "Then, inhibition of YAP1 expression is essential for pancreatic cancer targeted therapy." (PMID 33648545, 2021). "In particular, using the Oncomine database and Gene Expression Profiling Interactive Analysis (GEPIA) database, we found that YAP1 is differentially expressed between tumor tissues and control tissues in a number of cancers and in particular, is elevated in pancreatic cancer." (PMID 34150844, 2021). "Therefore, the regulation of YAP1 by WDR3 was found to be dependent on GATA4 in pancreatic cancer cells." (PMID 33648545, 2021). "CRISPR-Cas9 and shRNA were used to silence YAP1 expression in pancreatic cancer cells." (PMID 34094936, 2021). "Finally, the combination of WDR3 silencing and administration of the YAP1 inhibitor TED-347 had a synergistic inhibitory effect on the progression of pancreatic cancer." (PMID 33648545, 2021).
pancreatic cancer (continued). "Our findings indicate that YAP1 is an important prognostic biomarker for pancreatic cancer and may play a regulatory role in the remodeling of the extracellular matrix." (PMID 32054505, 2020). "Although the clinical utilization for such treatment remains to be determined, YAP1 as a biomarker may aid in the individual prognostication of patients diagnosed with pancreatic cancer and the selection of precision therapy." (PMID 32054505, 2020). "Here we evaluate the biomarker potential of YAP1 in pancreatic cancer tissue." (PMID 32054505, 2020). "The prognostic utility of YAP1 was evaluated using mRNA expression data from 176 pancreatic cancer patients in The Cancer Genome Atlas (TCGA), as well as protein expression data from immunohistochemistry analysis of a local tissue microarray (TMA) cohort comprising 140 pancreatic cancer patients." (PMID 32054505, 2020). "Therefore, to clarify the prognostic role of YAP1 protein expression in pancreatic cancer, additional studies based on larger cohorts are needed." (PMID 32054505, 2020). "This suggests that impairing nuclear YAP1 accumulation may be a promising therapeutic strategy to treat pancreatic cancer." (PMID 31897243, 2020). "We thus interpret that YAP1 may function as a marker for poor prognosis and disease relapse in pancreatic cancer patients." (PMID 32054505, 2020). "In addition, knockdown of eIF5A significantly inhibited endogenous PEAK1 and YAP1 expression, leading to tumor initiation in pancreatic cancer." (PMID 33200656, 2020). "The present results suggest that the novel YAP1–NMU axis might be a diagnostic marker for predicting the progression and outcomes of patients with pancreatic cancer, as well as a therapeutic target." (PMID 31575084, 2019). "This is the first report showing that YAP1/TEAD directly regulate NMU, indicating that a YAP1/TEAD/NMU pathway may be important for YAP1-dependent tumor metastasis and the poor outcome of pancreatic cancer." (PMID 31575084, 2019). "Previously it was also shown that miR-141 inhibited the expression of YAP1 in pancreatic cancer." (PMID 30041660, 2018). "In addition, the genes DUSP6, PIK3CA and YAP1 play critical roles in pancreatic cancer oncogenesis and tumor maintenance, which consequently impacts survival outcome." (PMID 30517129, 2018). "Our study demonstrates that after the knockdown of PKCι, the expression of the transcriptional co-activator YAP1 is decreased, which hinders the expression of the downstream target gene Mcl-1, and subsequently sensitizes pancreatic cancer MiaPaCa and PANC-1 cells experssing mu-Kras to apoptosis." (PMID 30214681, 2018). "In pancreatic cancer, YAP1 also portends a novel mechanism for an oncogenic gene." (PMID 26885617, 2016). "At lower cell densities (20–70%), the YAP1 protein was present in both the cytoplasm and nucleus in the two pancreatic cancer cell lines, BxPC-3, and PANC-1, whereas in the immortalized normal pancreatic ductal epithelial cell line, HPDE6, YAP1 was not detectable in the cytosolic fraction." (PMID 22396793, 2012). "YAP1 and its downstream effectors represent potential new therapeutic targets in pancreatic cancer." (PMID 22396793, 2012). "This perhaps indicates that, in addition to the upregulation of YAP1 protein expression, components of the Hippo pathway that regulate YAP1 localization (phosphorylation) might also be dysregulated in pancreatic cancer." (PMID 22396793, 2012). "Furthermore, treatment with YAP1 siRNA oligonucleotides diminished the anchorage-independent growth on soft agar of pancreatic cancer cells, suggesting a role of YAP1 in pancreatic cancer tumorigenesis." (PMID 22396793, 2012). "Summary of YAP1 immunostaining in pancreatic tumors and adjacent normal samples." (PMID 22396793, 2012). "We hypothesized that in pancreatic cancer cells such regulation of YAP1 localization by cell density is diminished." (PMID 22396793, 2012). "In this study, we sought to elucidate the role of YAP1 in pancreatic cancer." (PMID 22396793, 2012).
pancreatic cancer (continued). "Therefore, the simultaneous inhibition of ATF5 and YAP1 may be an effective therapy for pancreatic cancer." (PMID 40124511, 2025). "Interestingly, a recent molecular study revealed that inhibition of DCLK1 could downregulate PD-L1 expression through the Hippo-YAP1 signaling pathway in human pancreatic cancer." (PMID 39781521, 2025). "Importantly, YAP1 knockdown reversed the adverse effects of GPRC5A on pancreatic cancer cells." (PMID 36735162, 2023). "However, the interaction between GPRC5A and YAP1 in pancreatic cancer is unclear." (PMID 36735162, 2023). "Moreover, we evaluated the effects of irbesartan in the KPC mouse model and found that irbesartan significantly reduced c-Jun expression, Hippo/YAP1 activity, and the expression levels of stemness and iron metabolism genes in pancreatic tumors in the KPC mouse model." (PMID 37143164, 2023). "Moreover, we show that the proliferation and migration induced by GPRC5A in pancreatic cancer could be rescued by inhibiting YAP1 expression." (PMID 36735162, 2023). "Similarly, our results indicated that GATA4 could function as a transcription factor to induce YAP1 expression and activate the Hippo signaling pathway, which resulted in pancreatic cancer progression." (PMID 33648545, 2021). "Furthermore, WDR3 silencing could significantly decrease the proliferative and invasive abilities of pancreatic cancer cells by inducing YAP1 inhibition, which was found to rely on the interaction between WDR3 and GATA4." (PMID 33648545, 2021). "We employed the KM plotter database to explore the effect of YAP1 expression on the survival of patients with cancers showing the most obvious expression differences between tumor tissues and normal tissues (i.e., breast, colorectal, esophageal, gastric, lung, and pancreatic cancers)." (PMID 34150844, 2021). "Furthermore, WDR3 activated the Hippo signaling pathway by inducing yes association protein 1 (YAP1) expression, and the combination of WDR3 silencing and administration of the YAP1 inhibitor TED-347 had a synergistic inhibitory effect on the progression of pancreatic cancer." (PMID 33648545, 2021). "Furthermore, the relationship between YAP1 and molecular subtypes of pancreatic cancer is unknown, which may affect our results." (PMID 33123286, 2020). "However, little is known about the role of YAP1 and related genes in pancreatic cancer." (PMID 31575084, 2019). "YAP1 gene locus 11q22 is found amplified in myriad tumors spanning liver, lung, esophagus, mammary gland carcinomas, oral squamous cell carcinoma and medulloblastomas, whereas YAP1 overexpression has been identified in lung, colorectal, hepatocellular, ovarian, prostate and pancreatic cancer cells." (PMID 30214681, 2018). "Hence, 14-3-3σ and YAP1 may cooperate and require each other in pancreatic cancer cell survival against gemcitabine treatment." (PMID 26894857, 2016). "Under hypoxia, enhanced nuclear accumulation of YAP1, a component of Hippo pathway, also promotes EMT and invasiveness of pancreatic cancer cells." (PMID 40680814, 2025). "While ionizing radiation (IR) and YAP1 inhibition synergize to promote immunogenic cell death (ICD), enhance CD8+ T cell infiltration, and improve survival in patients with pancreatic cancer." (PMID 40977060, 2025). "YAP1 is a context-specific driver for PDAC, and its activation allows pancreatic cancer cells to bypass oncogenic KRAS dependency." (PMID 39458993, 2024). "The results showed that GPRC5A positively regulated YAP1, CYR61, cyclin D1, c-Myc and CTGF expression at the transcriptional level, as evidenced by overexpression and knockdown of GPRC5A in pancreatic cancer cells." (PMID 36735162, 2023). "Activation of YAP1 in acinar cells upregulated JAK-STAT3 signaling and promoted the development of pancreatic cancer." (PMID 36479120, 2022). "In pancreatic cancer, the nuclear localization signal of HNRNPK transcriptionally drives the activation of YAP1 and regulates cancer progression." (PMID 36439880, 2022).
pancreatic cancer (continued). "Therefore, YAP1 may be an effective predictor of digestion molecular markers for surviving systemic malignancies, especially pancreatic cancer, which can provide a new target for the treatment of digestive system tumors such as pancreatic cancer." (PMID 35911146, 2022). "Of note, YAP1 and TAZ can regulate the direct activation of the JAK-STAT3 signaling pathway to regulate pancreatic cancer in mouse models." (PMID 33946266, 2021). "Silencing WDR3 significantly decreased the expression levels of YAP1 and the downstream target genes CTGF and CYR61 in pancreatic cancer." (PMID 33648545, 2021). "YAP1 is highly expressed in several solid tumors, such as HCC and gastric, colorectal, lung, breast, and pancreatic cancers, and is related to prognosis." (PMID 33495421, 2021). "Increased levels of SMAD7 were observed in approximately 50% of pancreatic cancer cases, with increased SMAD7 and YAP1 mRNA expression found to contribute to resistance against TGF-β signaling in this condition." (PMID 33763375, 2021). "YAP1 has been widely correlated with asthma, and also known to influence disease progression by mediating HIF-1α in liver cancer and pancreatic cancer." (PMID 33980319, 2021). "Combined with the inhibition of YAP1 transcription induced by WDR3 knockdown, TED-347 treatment further enhanced the ability of WDR3 silencing to inhibit pancreatic cancer progression." (PMID 33648545, 2021). "In this transcriptome- and proteome-based study, we identified YAP1 as an indicator of poor OS and DFS in patients with pancreatic cancer." (PMID 32054505, 2020). "We performed RT-PCR with YAP1 specific primers flanking the alternatively spliced regions and cDNA from indicated PDAC cell lines and pancreatic cancer PDX cells, with peripheral blood mononuclear cells (PBMCs) as a control." (PMID 32292505, 2020). "In order to assess if LW6 has an effect on YAP1, we treated pancreatic cancer cell lines with 80 μM LW6 and assessed the protein concentration and nuclear localization of YAP1." (PMID 31897243, 2020). "Another paper reported that insulin receptor and G protein-coupled receptor cross-talk and activate YAP1 and TAZ in pancreatic cancer cells and that the activation is cancelled by PI3K inhibitor." (PMID 32267872, 2020). "Next, the four datasets of pancreatic cancer were analyzed using Pearson’s correlation analysis to determine the relationship between NMU and YAP1 mRNA expression." (PMID 31575084, 2019). "Increased levels of YAP-1 and Epidermal Growth Factor Receptor (EGFR) activation have been previously reported to be compensatory mechanisms to KRAS inhibition in pancreatic cancer cells." (PMID 31451509, 2019). "To determine the prognostic value of YAP1 and NMU expression in patients with pancreatic cancer, we compared the outcomes of patients with low expression (n = 87) and high expression (n = 87) of these proteins." (PMID 31575084, 2019). "The MIA PaCa-2 cell line, which has the lowest expression levels of YAP1 and NMU among the pancreatic cancer cell lines tested, was chosen as an adequate in vitro tumor model." (PMID 31575084, 2019). "Taken together, the results of the adhesion and migration assays, investigation of molecular changes, and xenograft mouse model suggest that YAP1 plays an important role in NMU expression and affects the metastatic properties of pancreatic cancer." (PMID 31575084, 2019). "Intriguingly, YAP1 is able to functionally compensate for oncogenic KRAS in colorectal and pancreatic cancer mouse models, which is consistent with the fact that RAS mutation and PKN1 mutation are mutually exclusive in the set of ERMS tumors presented here." (PMID 25768946, 2015). "Six pancreatic cancer cell lines (BxPC-3, CFPAC-1, HPAF-II, Hs 766T, MIA PaCa-2, and PANC-1) exhibited high to moderate protein levels of YAP1." (PMID 22396793, 2012).
pancreatic cancer (continued). "Some small‐molecule inhibitors, such as dasatinib, along with statins and topoisomerase inhibitor A35, acted as effective YAP1 inhibitors in renal cell carcinoma and pancreatic cancer, while their effects on YAP1 were found to be nonspecific and indirect." (PMID 39968498, 2025). "Similarly, YAP1 upregulates PD-L1 transcription in EGFR-TKI-resistant lung adenocarcinoma (LUAD) cells, yet in pancreatic cancer, DCLK1 suppresses PD-L1 via the Hippo pathway, highlighting tissue-specific regulatory circuits." (PMID 40977060, 2025). "In a sample of 48 pancreatic cancers, YAP1 expression levels did not significantly differ, nor were they notably correlated with the presence of PNI." (PMID 38567163, 2024). "Our results suggest that MST1/2 and LATS1/2 protein did not change markedly based on modulation of GPRC5A expression, which indicated that the regulation of YAP1 by GPRC5A is independent of LATS1/2 kinase in pancreatic cancer cells." (PMID 36735162, 2023). "To further determine the role of YAP1 in GPRC5A-mediated function in pancreatic cancer, we upregulated YAP1 using YAP1 plasmid with or without downregulation of GPRC5A in pancreatic cancer cells." (PMID 36735162, 2023). "In pancreatic cancer, differential hydroxymethylation of genes related to pancreas development or function (GATA4, GATA6, PROX1, ONECUT1, MEIS2), and cancer pathogenesis (YAP1, TEAD1, PROX1, IGF1) have also been shown to reliably identify pancreatic cancer from peripheral blood samples." (PMID 36835649, 2023). "Part of these genes have been reported in basic studies of pancreatic cancer and are closely related to the invasion and metastasis of pancreatic cancer according to the literature, including MYC, CDH2, SNAI1, YAP1, SOX2." (PMID 35237592, 2022). "Furthermore, by overexpressing YAP1 in WDR3 silenced PANC-1 cells, we found that overexpressed YAP1 reversed the inhibition of the proliferation and invasion ability in pancreatic cancer cells induced by WDR3 silencing." (PMID 33648545, 2021). "Since WDR3 silencing could inhibit YAP1 expression at the mRNA and protein levels, we hypothesized that The WDR3 knockdown enhanced the anti-pancreatic cancer effect of YAP1 inhibition." (PMID 33648545, 2021). "Nonetheless, the role of PKCι in Kras-mediated activation of YAP1 signaling in pancreatic cancer has not been investigated." (PMID 30214681, 2018). "Additionally, treatment of pancreatic cancer cell lines, BxPC-3 and PANC-1, with YAP1-targeting siRNA oligonucleotides significantly reduced their proliferation in vitro." (PMID 22396793, 2012). "Nevertheless, whether GPSM2 contributes to pancreatic cancer progression through the regulation of YAP1 has not yet been elucidated." (PMID 42231052, 2026). "We hypothesized that YAP1 might also regulate the tropism of tumor cells for nerves in pancreatic cancer, but the experimental outcomes did not meet our expectations." (PMID 38567163, 2024). "This might be due to the high incidence of PNI in pancreatic cancer or YAP1 not playing a major role in the neural tropism of pancreatic cancer cells." (PMID 38567163, 2024). "Interestingly, we downregulated YAP1 using siRNA with or without GPRC5A overexpression in pancreatic cancer cells." (PMID 36735162, 2023). "Regardless of whether the pancreatic cancer is treated or not, the median survival time of patients with the high expression of YAP1 is shorter than that of patients with low expression." (PMID 35911146, 2022). "In this study, we investigated whether PAF1 is required for the YAP1-mediated PDAC development and whether CA3 and verteporfin, small molecule inhibitors of YAP1/TEAD transcriptional activity, diminish pancreatic cancer (PC) cell growth by targeting the PAF1/YAP1 axis." (PMID 36180487, 2022).